GSK3B (glycogen synthase kinase 3 beta)
Diseases named in the same sentence as GSK3B in open-access papers (continued):
Sharing a sentence is not in itself a finding about the gene and the disease.
tumor (continued). "In addition, we found that SALL4 could exert its tumor-promoting effect via modulating Akt/GSK-3β axis and VEGFA expression." (PMID 32513235, 2020). "Importantly, GSK-3β-mediated tumor growth and proliferation was confirmed in in vivo experiment." (PMID 31938062, 2020). "Therefore, it is speculated that MST4 may suppress HCC cell proliferation and tumor growth via inhibiting cell cycle progression by inactivating PI3K/AKT/GSK3β pathway." (PMID 32742458, 2020). "Therefore, its role in cell biology and thereby in tumor progression is entirely dependent on the cell context, and it is essential to study GSK3β as a central player regulating the fate of the cell rather than merely as a regulator of the Wnt signaling pathway." (PMID 30845991, 2019). "Signaling pathways that inactivate GSK-3β, such as phosphatidylinositol 3 kinase/Akt and mitogen-activated protein kinase, may promote the cell cycle, anti-apoptosis, and invasion, thus facilitating tumor progression." (PMID 30709379, 2019). "In a variety of tissue cells and tumor cells, the activation of GSK-3β may further activate apoptosis-related protein kinase family caspase 3 and caspase 9, induce decomposition of nucleoprotein and shear fracture of DNA strand, and ultimately mediate apoptosis." (PMID 30237226, 2019). "Based on our findings, we propose that GSK3β inhibitors are promising candidates for combining with standard-of-care chemotherapy for the treatment of a subset of TNBCs, in particular for claudin-low subtypes to prevent their progression, emergence of chemoresistance, and tumor recurrence." (PMID 30845991, 2019). "In addition to an impairment of the GSK3β-directed β-TrCP pathway, aberrant accumulation of Nrf2 is augmented by inhibition of the Keap1-based proteasome-mediated degradation in Nrf1α−/−-derived tumor cells." (PMID 30562963, 2018). "Also, the expression levels of miR-410 and Gsk3β may be correlated to clinicopathological differentiation in NSCLC tumor specimens." (PMID 28076327, 2017). "Interestingly, IL-6 is also upregulated (fold change 7.317) in the combination group, and we found that IL-6 together with increased compressive force led to enhancement of positive feedback that controls EMT and tumor progression via the Akt/GSK-3β/β-catenin signaling pathway." (PMID 28846080, 2017). "Also, the high level of miR-410 and low expression of Gsk3β might be correlated to clinicopathological differentiation in NSCLC tumor specimens." (PMID 28076327, 2017). "However, little is known about the role of GSK3β in epigenetic regulation during tumor development." (PMID 27494834, 2016). "Interestingly, in the harvested OLA1-KD tumor tissues, we also observed over-activation of GSK3β, as reflected by decreased GSK3β phosphorylation at Ser-9 (GSK3β-p) and diminished expression of Snail, a downstream target of GSK3β." (PMID 26655089, 2016). "However, the application is complicated by findings that GSK3β behaves as a tumor suppressor, but may promote cell proliferation in different types of cancer." (PMID 27087918, 2016). "Moreover, overexpression of GSK-3β inhibited angiogenesis and tumor growth in vivo." (PMID 26388612, 2015). "Furthermore, phosphorylation of cyclin D1 by GSK-3β promotes its export by facilitating its association with CRM1 and the abrogation of phosphorylation results in its nuclear localization, thus promoting subcutaneous tumor formation in SCID mice." (PMID 26274615, 2015). "Our results demonstrate that inhibitors of GSK3β reduce phosphorylation of PAX3-FOXO1 at Ser201 and that inhibition of this event, either through small molecule inhibitors or mutational analysis reduces migration, invasion and proliferation in two independent ARMS tumor cell lines." (PMID 25821947, 2015). "GSK3β has many effects that could contribute to tumor development." (PMID 26310325, 2015). "However, GSK-3β may act either as a tumor promoter or tumor suppressor, depending on the cell context." (PMID 25591548, 2015).
tumor (continued). "Our data allows us to further understand the biological processes underlying NDRG1-associated tumor aggressiveness, and also suggests new avenues for developing therapeutic approaches for HCC, such as through the disruption of NDRG1 interaction with GSK-3β and/or Nur77." (PMID 26359353, 2015). "In addition, our model suggested that GSK3-β might play a tumour suppressor role in CAC by inhibiting CYCLIND1 and MDM2 in the pro-tumor inflammatory microenvironment." (PMID 26446703, 2015). "In addition, lithium chloride, a GSK-3β inhibitor, could attenuate Tg-mediated enhanced tumor growth, because Tg-induced apoptosis was prevented by GSK-3β inhibition." (PMID 25514597, 2014). "Although it remains controversial whether GSK3β is a “tumor suppressor” or “tumor promoter” in regulation of neoplastic transformation and tumor progression, GSK3β expression level was found to be higher in liver tumors than in normal liver tissues in a mouse model of hepatic carcinogenesis." (PMID 25277196, 2014). "We also observed increased phospho-GSK3β (p<0.008 compared to control and p<0.005 compared to γ radiation), indicating inactivation and thus inability of the protein to phosphorylate β-catenin, in 56Fe-irradiated tumor samples relative to control and γ radiation." (PMID 23555653, 2013). "Thus, we speculate that GSK3β may positively promote regulation of actin cytoskeleton and tumor invasion." (PMID 22363707, 2012). "However, there is little evidence that links GSK3β inactivation or loss of GSK3β expression with tumor development." (PMID 24212624, 2011). "Thus, we propose that Gsk3β downstream genes other than c-Myc may regulate the tumor-like growth of ESCs, which play independent roles from maintaining the self-renewal of ESCs." (PMID 21731714, 2011). "These and other findings suggest that GSK3β may act as a tumor suppressor protein in these setting." (PMID 21660227, 2011). "Interestingly, we also found that PMS2 expression was negatively correlated with GSK-3β inactivation in tumor tissues, indicating that activated GSK-3β may stabilize PMS2 production directly." (PMID 20178594, 2010). "Furthermore, in vivo xenograft studies also showed inconsistent role of GSK-3β in tumor promotion." (PMID 20704706, 2010). "We again observed that GSK3B inhibition significantly reduced the wt53BP1 SB28 cell survival fraction and inhibited tumor growth, measured by tumor volume and weight at day 26 following PARPi." (PMID 41243969, 2025). "Consistent with in vitro findings, xenograft tumor tissues from ARPC1B-knockdown groups exhibited significantly reduced protein levels of β-catenin, p-GSK3β, c-Myc, and cyclin D1 (p < 0.05)." (PMID 41050079, 2025). "Given that GSK-3β plays a role in EMT regulation, it is plausible that it also influences tumor stemness, immune evasion, and drug resistance." (PMID 41321870, 2025). "Our results demonstrate, for the first time, that miR-224-3p is loaded into EVs mediated by hnRNPA1 and that exo-miR-224-3p promotes tumor lymphangiogenesis and LNM through the GSK3B/β-catenin/PROX1 pathway." (PMID 39866224, 2025). "Toward this end, we investigated MGST1 function in LSCC cells and observed that silencing MGST1 significantly inhibited tumor cell proliferation, migration, and invasion, likely through downstream suppression of PIK3CA, NF-KB, β-catenin and GSK3β." (PMID 40778224, 2025). "It was reported that csHSPA5 can promote tumor progression through activating PI3K/AKT, MAPK/ERK and GSK-3β/β-catenin signaling cascade in several cancers." (PMID 40765821, 2025). "IL-8 and mTOR counter oxidative stress by inhibiting GSK-3β, while IL-17 stimulates matrix metalloproteinase 7 (MMP7) expression, driving tumor progression through epithelial-mesenchymal transition." (PMID 40430079, 2025). "Future studies are warranted to understand how GSK-3β signaling in DCs influences the quality of CD8 T-cell memory across different vaccine platforms and tumor settings." (PMID 40649856, 2025).
tumor (continued). "Importantly, we also reveal that while GSK-3β deficiency in DCs enhances early/primary CD8 T-cell responses, it impairs the ability to support the generation and/or maintenance of memory CD8 T cells, which are crucial for long-term immune protection against tumor recurrence." (PMID 40649856, 2025). "Immunohistochemistry further confirmed decreased expression of p-GSK-3β, MMP-9, and MMP-13 in tumor tissues from ArcA-treated mice." (PMID 39948552, 2025). "As we approved, through binding with GSK-3β protein, TRIM47 can enhance ADAR protein stability and ubiquitination so that TRIM47 endorses ADAR-mediated promotion of tumor migration and survival capability." (PMID 40618019, 2025). "This study is the first to demonstrate that lncRNA LOC610012 inhibits CMT cell proliferation, migration, and invasion, as well as tumor growth in vivo, by regulating the PTGS2/EP3/GSK-3β axis." (PMID 40643495, 2025). "Ginkgetin exerts its antitumor effects by modulating multiple oncogenic signaling cascades in tumor cells, notably the JAK/STAT, Wnt/β-catenin, AKT/GSK-3β, MAPK and ER pathway." (PMID 40762894, 2025). "The Wilcoxon signed-rank test was used to compare expression of GSK3β and S6K1 between paired tumor and normal tissue samples from TNBC patients." (PMID 41465855, 2025). "In a lung multicellular tumor spheroid (MTS) model, the GSK-3β inhibitor CHIR-99021 significantly increases the expression of CD31 and VE-cadherin, while inhibiting the expression of α-SMA and vimentin in HUVEC cells." (PMID 40650130, 2025). "The decrease of E-cadherin and the increase of N-cadherin and p-GSK3β are markers of tumor cell EMT, which is an important prerequisite for tumor cell invasion and metastasis." (PMID 40606986, 2025). "In this study, we demonstrate that the inhibition of GSK3B expression reduces β-catenin phosphorylation and promotes PROX1 transcription, leading to tumor lymphangiogenesis." (PMID 39866224, 2025). "AKT and GSK3β are core regulatory molecules of the PI3K/AKT/mTOR signaling pathway, playing important roles in tumor development and progression." (PMID 40860827, 2025). "With median values of 5.146 (tumor) and 4.469 (normal) for GSK3β and 7.057 (tumor) and 6.806 (normal) for S6K1, the expression level of both genes was proved to be significantly lower in tumor tissue compared to normal (p < 0.0001 for both GSK3β and S6K1)." (PMID 41465855, 2025). "Further, preclinical studies have demonstrated that inhibiting GSK-3β with 9-ING-41 (elraglusib) enhances efficacy of TILs and CD8+ T cells to tumor cells." (PMID 40075563, 2025). "In conclusion, miR-8485-mediated downregulation of UBN2, ETS1, MMS22L, GSK3B, and SLC44A1 inhibits tumor progression through mechanisms involving cell cycle arrest, metastasis inhibition, apoptosis induction, and choline metabolism." (PMID 40095604, 2025). "The synthetic lethality of GSK3β and FHIT has been validated in multiple FHIT-isogenic cell panels and in tumor xenograft models in vivo." (PMID 39762409, 2025). "Some miRNAs (miR-1246/92b-3p/27a-3p) enriched in Fn-Exs can directly suppress glycogen synthase kinase-3β (GSK3β) expression and activate Wnt/β-catenin pathway, thereby promoting CRC cell migration, and ultimately contributing to tumor metastasis." (PMID 39995663, 2025). "In vivo, CAFs promoted CRPC tumor growth and significantly increased the expression of Wnt3a, β-catenin, TCF4, LEF1, SDF-1, and CXCR4, along with an elevated p-GSK-3β/GSK-3β ratio." (PMID 40735647, 2025). "Induction of apoptosis and anti-proliferation, with alteration of GSK3β/β-catenin signalling, in addition to reduction of COX-2 level, and downregulation of tumours’ VEGF-R and VEGF-A." (PMID 40427522, 2025). "Our previous research indicated that increased GSK-3β expression was positively correlated with the cell death and metastasis of HCC cell lines, suggesting its role as a tumor suppressor in HCC." (PMID 40804393, 2025).
tumor (continued). "Total RNA was isolated from pairs of archived tumor and normal tissues of patients with TNBC in order to analyze the level of mRNA expression for GSK3β and S6 kinase 1 genes." (PMID 41465855, 2025). "By directly targeting several Wnt/β‐catenin antagonists including AXIN1, GSK3β and DKK1, miR‐31 promotes the Wnt signalling pathway and tumour development within mammary and small intestine." (PMID 38797942, 2024). "We observed that the promotion of tumor apoptosis and the reduction in cell colony formation induced by PQR309 plus gemcitabine were partially rescued by the overexpression of GSK-3β." (PMID 38555280, 2024). "By governing the AKT/GSK-3β pathway, PDCD6 emerges as a significant contributor to tumor progression in HCC." (PMID 39156976, 2024). "Previous studies have shown that Gas6 is able to regulate tumor cell migration and invasion through the JAK2/ERK, SRC, and Akt/GSK-3β/β-catenin pathways." (PMID 39451556, 2024). "As the marker of exhaustive CD8 T cells, HAVCR2 regulates EMT by crosstalking Akt/GSK-3β/Snail signaling pathway with SMAD7/SMAD2/ SNAIL1 Axis, implicating the dual role of Community 1-related immune genes in EMT and tumor immune." (PMID 38331768, 2024). "One of the studies discovered that exosomal GP73 secreted by tumor cells can enter other acceptor tumor cells with low GP73 expression, activating GSK-3β phosphorylation and inducing upregulation of MMP-1 and MMP-9, promoting tumor metastasis." (PMID 39845976, 2024). "GSK3B is involved in the PI3K–Akt signaling pathway, which can promote the proliferation, differentiation, and angiogenesis of tumor cells." (PMID 39628999, 2024). "In summary, PDCD6 plays a pivotal role in promoting tumor growth in HCC, primarily through its modulation of the AKT/GSK-3β signaling pathway." (PMID 39156976, 2024). "To confirm the GSK3β-PPARα signaling axis downstream of PIM kinase effectively alters LD accumulation in vivo, we assessed tumor tissues (n = 3 tumors/group) by western blotting alongside cell lysates exhibiting PIM1 induction." (PMID 38097734, 2024). "Next, we evaluated the effect of ULK1 overexpression on autophagy and tumor progression in 143B and U2OS cells with GSK3β knockdown." (PMID 39218913, 2024). "Patients whose tumour had high expression of MAP1LC3A, SNCA, and MAPT and low expression of CDK1, AP1S1, CASP3, TMPRSS6, and GSK3B inferred better overall survival than all other patients." (PMID 38642129, 2024). "Glycogen synthase kinase 3β (GSK3β) is a direct substrate of PIM1, and its tumor-suppressive effects on cancer cells are blocked by PIM1-induced phosphorylation, leading to increased cell migration and adhesion." (PMID 39227379, 2024). "ETS1, GSK3β, VEGFA, and YWHAZ were significantly upregulated in tumor tissues (p < 0.001), indicating their oncogenic roles in HNC progression." (PMID 39518147, 2024). "In CRC, PIK3CD is found to promote tumor cell proliferation and migration through activating AKT/GSK‐3β/β‐catenin axis." (PMID 38545256, 2024). "In tumor growth, STIM1 stabilizes the Snail1 protein by activating the CaMKII/AKT/glycogen synthase kinase 3 beta pathway." (PMID 38344399, 2024). "Capivasertib can enhance anti-tumour effects of docetaxel by targeting residual docetaxel-persister cells, independent of PTEN status, to induce apoptosis and DNA damage in part through GSK3β." (PMID 38396173, 2024). "It has been reported that activated AKT further phosphorylates the GSK-3β protein, inhibits the expression of E-cadherin, and promotes the process of EMT, which results in tumor migration and invasion." (PMID 38914958, 2024). "AKT activation further suppresses tumor suppressors such as FOXO and GSK-3β, leading to the inhibition of apoptosis and enhanced cell survival." (PMID 39769140, 2024). "Plasmodium infection blocks the TGFβ/CCR10/PI3K/Akt/GSK-3β signaling pathway, thereby inhibiting epithelial–mesenchymal transition (EMT) of the cancer cells and preventing tumor metastasis and recurrence." (PMID 38807760, 2024).
tumor (continued). "Immunostaining of tumor tissue sections from lung biopsies showed weak positive signals for PIM1, p-GSK3β (Ser9), and Vimentin before treatment, which subsequently became strong positive signals upon development of acquired osimertinib resistance." (PMID 39227379, 2024). "GSK3B is expressed as glycogen synthase kinase 3β (GSK-3β), a critical inhibitor of the Wnt/β-catenin signaling pathway, and is generally suppressed in tumor cells." (PMID 39323640, 2024). "The overexpression of miR-29a, miR-221, miR-222, and miR-130b stimulates the proliferation of tumor cells by activating PI3K/AKT and targeting several tumor suppressors, such as glycogen synthase kinase 3β (GSK3β) and PTEN." (PMID 38812786, 2024). "Afterward, it was found that NDRG1 exacerbates HCC initiation via enhancing crosstalk between fibroblasts and tumor cells and promotes the growth of HCC cells by interacting with GSK-3β and Nur77 to prevent β-catenin degradation." (PMID 37406019, 2023). "We then confirmed this result in qRT-PCR and immunohistochemical staining experiments, and our vitro studies demonstrated that SQLE knockdown inhibited tumor cell proliferation and metastasis through the PTEN/AKT/GSK3β signaling pathway." (PMID 37770925, 2023). "Inhibiting GSK3β with a GSK3β inhibitor in TAMs reduces the proliferation, migration and invasion of HCC cells in vitro and inhibits tumour growth in vivo improving the sensitivity of the anti-PD1 therapy." (PMID 37894344, 2023). "Dr. Abdulrahman found that BI-D1870 can mitigate tumor growth and potentiate cisplatin activity in LUAD cells through phospho-GSK-3β and osteopontin." (PMID 37046682, 2023). "The relationship between methylation and expression of genes GSK3B, THBS1, and PTPN1 manifested a positive correlation in most tumour types, whereas this was reversed for genes PPP1R14D." (PMID 37815881, 2023). "Overall, our findings suggest that TGFβ can activate GSK3β to stabilize NDRG1, which results in NF-κB activation as an effector of tumor progression." (PMID 36594086, 2023). "We characterize the critical regulators of the FASN overexpression in tumor development, including EGF, CSN6, GSK3β, and E3 ligase FBXW7β." (PMID 37202390, 2023). "Based on these results, GSK-3β functions as a tumor promoter in RCC; however, the role of miRNAs in the regulatory mechanism of GSK-3β is unclear." (PMID 37754254, 2023). "Therefore, the GSK3β-dependent macrophage reprogramming ability of MTX could be also taken into consideration when designing combined therapeutic strategies to target myeloid cells in the tumor stroma." (PMID 36380627, 2023). "Our results indicate that DKK1 inhibition significantly enhances the anti-tumor efficacy of sorafenib by inhibiting the PI3K/Akt and Wnt/β-catenin pathways via regulation of GSK3β activity, suggesting a novel therapeutic strategy for HCC." (PMID 38012711, 2023). "In conclusion, we found that DKK1 inhibition significantly enhanced the anti-tumor efficacy of SOR by inhibiting the PI3K/Akt and Wnt/β-catenin pathways and both pathways were connected via GSK3β in HCC." (PMID 38012711, 2023). "Immunohistochemistry images derived from the HPA database showed that GSK3B and IL18 expression at protein level in tumour tissues was elevated in contrast with that in normal tissues, in line with findings of RNA expression levels." (PMID 36743929, 2022). "AR79, an inhibitor of GSK3β, increases the proportion of ALDHhigh CD133+ cancer stem cell-like in PCa cell lines, promoting tumor growth and tumor-induced bone remodeling." (PMID 36300093, 2022).